CD4 (CD4 molecule)
Diseases named in the same sentence as CD4 in open-access papers (continued):
Sharing a sentence is not in itself a finding about the gene and the disease.
polyp (11 papers, 2014 to 2025). A usually exophytic mass attached to the underlying tissue by a broad base or a thin stalk. "Taken together, this suggested that treatments associated with decreased polyp burden resulted in more activated CD4 and CD8 T cells and fewer macrophages in polyps, and further that there was a shift from anti-inflammatory toward pro-inflammatory macrophages in the spleen." (PMID 30881361, 2019). "Herein, the densities of TAMs, TANs, activated T cells, and CD4+ T cells in the TiME of colorectal adenoma were positively correlated with the polyp size." (PMID 40149674, 2025). "It has been seen that, as the FAP disease progresses (i.e. within FAP polyp samples), the M2 macrophage started to show several interactions with other cell types, specifically CD4+ T cells, B cells and M1 macrophages." (PMID 39605357, 2024). "Since a decrease was also seen in colon mRNA levels of CD4 and Arg-1, it is plausible that the decreased polyp infiltrate also consisted of CD4+ T cells and type-2 macrophages." (PMID 28410235, 2017). "Intracellular cytokine staining was performed on CD4+ T cells expanded from polyp explants and peripheral blood in parallel to establish the TH cell cytokine profile." (PMID 26684290, 2016). "The results showed that the proportion of CD8+ T cells in polyp tissues was significantly higher than in control tissues, and the percentage of CD4+ T cells in polyp tissues was less than in control sinonasal tissues (P < 0.01)." (PMID 27468819, 2016). "In this study, we enrolled NP patients from southern China and found that these polyp tissues displayed a significant increase in CD8+ T cells and a relative deficiency of CD4+ T cells compared with control sinonasal tissues." (PMID 27468819, 2016). "In FAP polyp samples, macrophages and CD4+ T cells colocalize within a region." (PMID 39605357, 2024). "Higher percentages of iNKT subsets, including CD4+ iNKT cells (1.95-fold), HLA-DR+ iNKT cells (1.48-fold), and PD-1+ iNKT cells (1.47-fold), were also observed in polyp tissues than in control mucosa; moreover, HLA-DR+PD-1+ iNKT cells were also elevated (1.69-fold) in polyp samples." (PMID 35720287, 2022). "Notably, the colorectal polyps examined in the Tokyo trial persisted throughout the one-year trial period in the patients ingesting 3 g bLF daily, indicating that the polyp-associated CD4+ and NK did not induce an immune response against the polyps." (PMID 24867408, 2014). "While computing Pearson correlation coefficient for all the tissue samples involved, we find significant correlation between activated CD4+ T cells and M1 macrophages (p = 0.034) within normal and FAP mucosa when compared to that of FAP polyp and adenocarcinoma samples." (PMID 39605357, 2024). "Still, while anti–PD-1 treatment was sufficient to enhance Tbet expression in both polyp iNKT cells and systemically in CD4 T cells, this treatment only reduced the size of intestinal polyps, but not polyp numbers." (PMID 33193386, 2020).
prediabetes (11 papers, 2013 to 2025). "Our data clearly reveal an important association of prediabetes with modified immune responses (both CD4+ and CD8+ T cell) in latent TB infection." (PMID 28558065, 2017). "Thus, our data reveal that prediabetes is associated with alterations in the CD4+ and CD8+ T cell response to TB antigens." (PMID 28558065, 2017). "Prediabetes prevalence was similar by CD4 counts, ART use and duration of ART use, although point‐estimates were higher in ART naïve and participants with shorter duration of ART use." (PMID 36924213, 2023). "We also analyzed the population of CD28−CD57+ senescent CD4+ and CD8+ T cells in the patients with prediabetes according to diagnostic criteria for prediabetes." (PMID 30867412, 2019). "In addition, we analyzed the correlation between serum GDF15 level and senescent CD4+ or CD8+ T-cell numbers in the patients with prediabetes." (PMID 30867412, 2019). "The production of perforin was also greater in the senescent CD4+ and CD8+ cells from the patients with prediabetes." (PMID 30867412, 2019). "In consistent with previous reports, IFN-γ and TNF-α production in total CD4+ and CD8+ T cells were increased in patients with prediabetes." (PMID 30867412, 2019). "To compare the immunosenescence of T cells in PBMCs from normal controls and patients with prediabetes, we evaluated the frequency of CD57+ and/or CD28− T cells among the CD4+ and CD8+ T cells in the PBMCs from the study population." (PMID 30867412, 2019). "The population of IFN-γ and TNF-α producing total CD4+ and CD8+ T cells are significantly increased in the PBMCs from the patients with prediabetes compared with normal subjects." (PMID 30867412, 2019). "Therefore, we investigated the functional characteristics of senescent CD4+ and CD8+ T cells from normal controls and patients with prediabetes." (PMID 30867412, 2019). "CD4+CD28− T cells contained similar concentrations of ROS, regardless of serum glucose status, whereas CD8+CD28− T cells from the patients with prediabetes had a higher capacity to produce ROS than those from normal subjects." (PMID 30867412, 2019).
sialadenitis (11 papers, 2007 to 2026). Sialadenitis is an infection of the salivary glands. "The function of RORγt overexpression in naive CD4+ T cells has been elucidated in RAG deficient mice showing the development of pSS phenotype upon transfer of RORγt-overexpressing CD4+T cells that induce sialadenitis." (PMID 32971904, 2020). "It has been reported that RORγt overexpression induced severed spontaneous sialadenitis-like SS via RORγt overexpressed CD4+ cells and reduced Treg." (PMID 30189901, 2018). "Sex differences were observed in female NOD.H2h4 mice in which female mice developed increased severity of sialadenitis with higher CD4+ T cells producing Th2 and Th17 cytokines." (PMID 26453623, 2015). "Moreover, transfer of CD4+ T cells overexpressing RORγt into Rag2−/− mice induced sialadenitis." (PMID 41300932, 2025). "Moreover, RORγ-transgenic mice, an established SS-like sialadenitis mice model, were reported to induce the expression of IL-2-mediated CD25 and CD69 on CD4+ T cells." (PMID 33726818, 2021).
simian immunodeficiency virus infection (11 papers, 2007 to 2023). An infection affecting monkeys, chimpanzees, and other non human primates caused by a HIV-like virus. "In simian immunodeficiency virus infection, DN T cells develop CD4 T cell functions that parallel the loss of CD4 T cells and protect against viral dissemination." (PMID 24098583, 2013). "The hallmark of Human Immunodeficiency Virus and Simian Immunodeficiency Virus infection in disease-susceptible species is the progressive decline of the CD4+ T cell population and heightened immune activation, which by itself can contribute to CD4+ T-cell death." (PMID 30161247, 2018). "In this study, we demonstrate that in early simian immunodeficiency virus infection, depletion of CD4 T cells is primarily due to pyroptosis." (PMID 36000842, 2022). "has shown that CD4+ T cells in simian immunodeficiency virus infection become altered and undergo apoptosis once trapped within NET chromatin." (PMID 34899751, 2021). "Indeed, depletion of intestinal CD4+ T cells that accompanies simian immunodeficiency virus infection selectively blunted the intestinal IL-17 response in rhesus macaques, allowing increased translocation of Salmonella to the mesenteric lymph nodes and spleen." (PMID 30216367, 2018).
Sleep disturbance (11 papers, 2021 to 2026). An abnormal pattern in the quality, quantity, or characteristics of sleep. "Over a third of PLWH reported sleep disturbances in this study, and participants with less income, higher CD4 counts, ART, exercise behavior, depressive symptoms, and higher stress levels were more likely to experience sleep disturbances." (PMID 34295273, 2021). "In contrast, the sleep disorder group showed significantly lower levels of peripheral lymphocyte count, CD3+ T cell proportion, CD4+ T cell proportion, immunoglobulin G, immunoglobulin A, immunoglobulin M, Complement C3, and Complement C4 (all P < 0.001)." (PMID 41584611, 2025). "In some studies, sleep disturbances find association with fatigue, a very common and debilitating symptom in PLWH, rather than HIV-related factors such as CD4 count or viral load." (PMID 40309785, 2025).
uremia (11 papers, 2013 to 2025). A clinical syndrome associated with the retention of renal waste products or uremic toxins in the blood. "Studies have identified an increased fraction of terminally differentiated CD8+ T-cells along with low proportions of CD4+ and high proportions of CD8+ T-cells as a marker of both age and uremia associated immune senescence." (PMID 28562595, 2017). "In this regard, it has been shown that monocyte function, cooperation and interaction between antigen presenting cells and CD4+ T cells are impaired in uremia." (PMID 24282790, 2013). "Notably, it has been reported that uremia-derived CD4+T cells had a reduced number of TCR/CD3 antigen receptor complexes and a skewed T cell receptor Vβ repertoire." (PMID 35720370, 2022). "In the remnant kidneys from NX mice, flow cytometry revealed an increase in the number of monocyte-like cells (CD68+F4/80-), CD4+, and CD8+ T-cells, suggesting that moderate uremia induced kidney inflammation." (PMID 27992511, 2016).
Ureteral obstruction (11 papers, 2013 to 2025). Obstruction of the flow of urine through the ureter. "In mice with unilateral ureteric obstruction, a model of renal interstitial fibrosis, CD4 expression is associated with increased gene expression and deposition of type I collagen in kidney tissue." (PMID 40223398, 2025). "Other authors have reported a protective role of CD4+ T-cells in a toxic injury model and in an unilateral ureteral obstruction (UUO) model." (PMID 29593222, 2018). "Our research investigated the effects of intravenously administered placenta mesenchymal stromal cells (PMSCs) or treatment with extracellular EVs (EVs) derived from PMSCs (PMSC-EVs) on the polarization of CD4+ T cells in rats with unilateral ureteral obstruction (UUO)." (PMID 32774389, 2020).
angioimmunoblastic T-cell lymphoma (10 papers, 2013 to 2025). A mature T-cell non-Hodgkin lymphoma, characterized by systemic disease and a polymorphous infiltrate involving lymph nodes and extranodal sites. "As CD4 is also frequently upregulated on subtypes of PTCL like angioimmunoblastic T-cell lymphoma, anti-CD4 CAR-T cells are another area of investigation." (PMID 38090582, 2023). "Angioimmunoblastic T-cell lymphoma (AITL) is a mature T-cell tumor classified under peripheral T-cell lymphomas (PTCLs), specifically derived from CD4+ follicular helper T (TFH) cells." (PMID 41008782, 2025). "This is the case of high-energy-demanding angioimmunoblastic T cell lymphoma (AITL), a highly aggressive cancer with poor survival rates, where malignant CD4+ PD-1high T cells show increased mitochondrial activity and Reactive oxygen species (ROS) accumulation." (PMID 40346022, 2025). "An important subset of T-cell lymphomas are lymphomas of CD4+ T-follicular helper (TFH) origin, whose proliferation is thought to lead to the development of angioimmunoblastic T-cell lymphoma (AITL), PTCL-FH type, and some follicular lymphomas and cutaneous T-cell lymphomas (CTCLs)." (PMID 35743749, 2022). "Angioimmunoblastic T-cell lymphoma (AITL) has a rich tumor microenvironment (TME) that typically harbors plenty of CD4+tumor infiltrating lymphocytes, (TIL)-T-cells (so called common AITL)." (PMID 36325319, 2022). "Angioimmunoblastic T-cell lymphoma (AITL) and about 20% of PTCL-not otherwise specified (PTCL-NOS) have similar gene expression signatures to the normal CD4+ T-cell subset follicular helper (Tfh) T-cells." (PMID 30242208, 2018).
avian influenza (10 papers, 2008 to 2025). Infection of domestic and wild fowl and other birds with influenza A virus. "For instance, it enhanced macrophage phagocytic activity and antibody titers against avian influenza in quails and increased CD4+ T lymphocyte counts and lysozyme activity." (PMID 41202602, 2025). "One study suggested that the poor antibody response to avian influenza vaccine was due to insufficient help from CD4+ T cells." (PMID 37853397, 2023). "Seasonal vaccine administration may enhance the frequency of reactive CD4 T cells, boosting the cross-subtype cellular immunity against avian influenza (H5N1)." (PMID 18258091, 2008). "This multiplicity of potential functions contributed by memory CD4 T cells, each conferred by distinct arrays of soluble mediators and cell surface proteins, presents a significant challenge for predicting and enhancing protective immunity to potentially pandemic strains of avian influenza." (PMID 26834750, 2016). "We suspect that this greater degree of CD4 T cell cross-reactivity may be responsible for the better antibody response to pH1N1 vaccination compared to avian influenza-derived vaccines and may also have served to temper disease progression during the initial spread of this virus." (PMID 26834750, 2016). "In this study, we found significantly higher frequencies of CD38 + CD4+, CD38 + CD8+, Tim-3 + CD4+ and Tim-3 + CD8+ T cells in patients with H7N9 avian influenza compared with those in the HCs." (PMID 25030090, 2014). "Moreover, B. subtilis spores, as adjuvants, were shown to enhance CD4+ and CD8+ T cell responses in vivo against avian influenza H9N2." (PMID 36838233, 2023).
carcinoma in situ (10 papers, 2017 to 2026). "Association studies were also done between the percentage of CD4+ Treg subsets and other clinical and pathological characteristics, including T grouping, histological grade, muscular invasion, lymphovascular invasion, perineural invasion, and carcinoma in situ." (PMID 33305045, 2020). "Among CD4+ T cells, the percentage of GATA3+FOXP3– cells and the percentage of GATA3+FOXP3+ cells were higher in invasive melanoma compared with in situ melanoma, while the percentage of GATA3–FOXP3+ cells remained similar." (PMID 36107619, 2022). "Changes in plasma membrane fluidity due to altered cholesterol and sphingolipid compositions can alter the expression and function of CD4 and CCR5 and HIV-1 cis infection (48, –, 50)." (PMID 29643243, 2018). "In the in situ carcinoma mouse models, intratracheal perfusion of V. parvula promoted Ki67 expression in tumor lesions (p = 0.0092) and reduced peripheral and tumor-associated CD3+ and CD4+ T-lymphocyte infiltration (p < 0.05) but did not affect CD8+ T-lymphocyte expression." (PMID 37452162, 2023). "People with HPV‐mediated anal lesions had faster rates of progression to carcinoma in situ (CIS) and to invasive carcinoma in people with versus without HIV, which was further enhanced by low CD4 counts." (PMID 40172095, 2025).
chorioamnionitis (10 papers, 2009 to 2026). A morphologic finding indicating inflammation of the fetal sac membranes. "Analysis of adaptive immune responses in chorioamnionitis-exposed infants has mainly focused on T cells, in particular CD4+ T cells." (PMID 32636848, 2020). "Elevated CD4 T cell proliferation was also observed immediately post birth in infants born to mothers with chorioamnionitis." (PMID 32152273, 2020). "This notwithstanding, infants born in the context of chorioamnionitis or those with an unstable clinical course exhibited significantly lower CXCL8-producing CD4 and CD8 T cells when compared to stable infants." (PMID 32152273, 2020). "Babies who had an unstable course or those born in the context of chorioamnionitis showed elevated levels of the activation marker CD69 on all T cell populations (CD4, CD8 and γδ) as well as on NK cells when compared to babies who had a stable postnatal course." (PMID 32152273, 2020). "Chorioamnionitis also changed the metabolic profile of CD4+ T cells, altering metabolites that are part of the tryptophan catabolism and glutathione detoxification pathway, which could be linked to the enhanced development of a Th1 response." (PMID 32636848, 2020). "Considering that lung inflammation may be a constant problem in preterm infants due to infection, chorioamnionitis, or ventilation, we simulated a simultaneous inflammatory trigger in vitro by activating CD4+ T cells using CD3/CD28 antibodies during exposure to surfactant." (PMID 27077658, 2016). "CD35 (also known to increase upon cell activation) was also elevated on both CD4 and CD8 T cells, significantly so in those infants exposed to chorioamnionitis." (PMID 32152273, 2020). "This chorioamnionitis‐induced immunosuppression includes the depletion of B and T lymphocytes in spleen, thymic involution, endotoxin hyporesponsiveness and lower CXCL8‐producing CD4 and CD8 T cells." (PMID 33006196, 2021). "We determined the frequency of CD4+ memory T cells in neonates born preterm, in the absence of clinical chorioamnionitis, and found that they had an increased percentage of memory T cells compared to infants born at term without complications." (PMID 21347427, 2011).
cystic fibrosis (10 papers, 2014 to 2024). Autosomal recessive disorder caused by pathogenic variants in the CFTR gene (cystic fibrosis transmembrane conductance regulator), which encodes a chloride and bicarbonate channel expressed in epithelial cells, and follow the diagnosis criteria. "Higher proportions CD40L+IL-2- CD4+ T cells were associated with cystic fibrosis patients infected with Mycobacterium abscessus, highlighting the potential of characterizing the precise profile of cytokine produced by CD4+ T cells in mycobacterial infections." (PMID 28241036, 2017). "Healthy individuals and patients with cystic fibrosis had robust antigen-specific memory CD4+ T cell responses to Pseudomonas aeruginosa that not only contained a Th1 and Th17 component but also Th22 cells." (PMID 24587305, 2014). "Similarly, Kreindler and coworkers reported that vitamin D3 attenuated in a TNFSF4-dependent manner Th2 immune responses to A. fumigatus mounted by CD4+T cells from cystic fibrosis patients with allergic bronchopulmonary aspergillosis." (PMID 33374839, 2020). "Comparison of demographics and CD4+ T cell subsets in control and cystic fibrosis groups." (PMID 25803862, 2015). "Addition of vitamin D3 can suppress this A. fumigatus-specific Th2 response in peripheral CD4+ T cells in patients with cystic fibrosis and ABPA." (PMID 26402698, 2015).
filariasis (10 papers, 2007 to 2025). "Indeed, severity of LE in filariasis patients is associated with magnitude of CD4+ T cell immune responses to filarial antigen." (PMID 33434186, 2021). "Phenotype absence in filariasis indicates T cell hyporesponsiveness, and the triggering of a CD4+ T cell response is usually necessary for the manifestation of the filariasis phenotype, which includes hydrocele, lymphedema, and elephantiasis." (PMID 40126325, 2025). "A study evaluating PBMC from patients with filariasis, showed that CD4+ T cells are the main source of IL-10 and the majority of these cells co-produced neither IL-4 nor IFN-γ." (PMID 33692784, 2021). "Hypo-responsive Th2 cells may fail to develop into memory cells as seen with exhausted CD8+ T cells, and consistent with this filariasis patients show contractions in their central memory CD4+ T cell pool." (PMID 23516361, 2013).